INS (insulin)
Diseases named in the same sentence as INS in open-access papers (continued):
Sharing a sentence is not in itself a finding about the gene and the disease.
Hyperglycemia (continued). "Moreover, in the smaller Hyperglycemia: Intensive Insulin Infusion In Infarction (HI-5) study with 240 patients, the mean blood glucose level after 24 hours was 8.3 mmol/L in the treatment group compared to 9.0 mmol/L in the conventional group (NS)." (PMID 17284309, 2007). "Impaired glycemic control has been associated with increased mortality in a heterogeneous population of critically ill patients, and van den Berghe and coworkers showed that preventing hyperglycemia with insulin substantially improved outcome in critically ill surgical patients." (PMID 17306016, 2007). "Furthermore, hyperglycemia can also induce atherosclerosis independently of insulin, e.g. through glycation of proteins and lipids and by increasing oxidative stress." (PMID 17958881, 2007). "In addition, insulin is essential in this study as it minimized the adverse impact of hyperglycaemia on the rate of GE." (PMID 18154642, 2007). "This study is based on the hypothesis that early intervention with insulin replacement prevents catabolism and the hyperglycaemia seen during the first week of life, in the VLBW preterm infant." (PMID 17692117, 2007). "Despite decreased glucose transporter expression and decreased insulin-mediated glucose transport, the rates of glucose uptake in the diabetic environment, are comparable to those observed in normal hearts, due to the prevailing hyperglycemia." (PMID 19936093, 2007). "Five DLTs were observed, one grade 3 hyperglycaemia with hyperosmolar coma at 3 mg m−2 requiring insulin and rehydration, and four DLTs at dose level of 5 mg m−2 day−1: (i) one anasarque and haematemesis, (ii) one life-threatening pulmonary aspergillosis, (iii) one skin rash and (iv) one scalp pain." (PMID 16847470, 2006). "The expected transient hyperglycemia responded appropriately to insulin." (PMID 17137499, 2006). "Hyperglycemia was completely normalized and adequate control was obtained using insulin therapy, making it difficult to conclude whether hyperglycemia and plasma insulin levels are modulators of the lymphocyte response." (PMID 17086304, 2006). "Exposure to hyperglycemia would increase the infant's production of insulin, and the possibility of exposure to hyperglycemia during pregnancy and increased risk of childhood and adult chronic diseases associated with impaired glucose metabolism is under study." (PMID 16736025, 2006). "Hyperglycemia can contribute to inflammation, and insulin has anti-inflammatory properties (e." (PMID 16111485, 2005). "However, in a landmark study, van den Berghe and coworkers showed that treating transient postoperative hyperglycaemia with intensive insulin therapy in a surgical intensive care unit (ICU) dramatically reduces mortality and morbidity." (PMID 15566589, 2004). "In univariate analysis, a positive association was found between postoperative hyperglycaemia and length of hospital stay (P < 0.001; ß = 0.053; standard error [SE] of ß = 0.014), but not with insulin administration (P = 0.5; ß = -0.56; SE of ß = 0.7)." (PMID 15566589, 2004). "Conversely, hyperthyroidism and GD contribute to hyperglycemia through various pathways, such as heightened appetite, enhanced glucose absorption in the intestines, increased glucose production in the liver, elevated lactate output and accelerated insulin clearance and breakdown." (PMID 41317333, 2026). "In principle, an artificial pancreas - a closed-loop insulin delivery system requiring patients to manually input insulin dosage according to the upcoming meals - could supply exogenous insulin to control the glucose levels and hence reduce the risks from hyperglycemia." (PMID 41766716, 2026). "Since hyperglycemia is thought to deleteriously affect tissue-level sensitivity of insulin action, we hypothesized that glucose-lowering by canagliflozin (Cana) improves the ability of insulin treatment to rescue the T1D-related decrease in bone strength." (PMID 41618015, 2026).
Hyperglycemia (continued). "The elevation of basal insulin, even within reference intervals, not only accelerates glucose uptake into cells but also produces false-negative results in standard clinical tests, thereby obscuring the detection of subclinical hyperglycaemia and early hyperinsulinaemia." (PMID 41586225, 2025). "Because of the rapid absorption of an SP-based diet that induced hyperglycemia and hyperinsulinemia in our experimental rats, we speculate that the increased glucose and insulin transported to the liver resulted in the abnormalities in the glucose metabolism we observed." (PMID 40074175, 2025). "Insulin concentrations may fall within population reference intervals, but are elevated relative to individual metabolic capacity, thereby masking subclinical hyperglycaemia (fasting glucose ≤ 5.7 mmol/L due to insulin-compensation) and subclinical hyperinsulinaemia (≥ 8 μIU/mL)." (PMID 41586225, 2025). "Furthermore, we examined whether HYA ameliorated postprandial hyperglycemia in the type 1 diabetes model rats administered bolus insulin immediately before OGTT." (PMID 39899133, 2025). "Poblete and Olmos reported that the hyperglycemia and hyperinsulinemia associated with GDM could stimulate the fetal pancreas to secrete excessive insulin, leading to excessive nutrients entering the fetus and fetal overgrowth and adiposity, with 15%–45% of GDM cases complicated by macrosomia." (PMID 40510888, 2025). "This may be combined with rapid-acting insulin to control mid-morning hyperglycemia from breakfast." (PMID 40760593, 2025). "On the other hand, the time-dependent alterations at the distal gut may refer to a prompt defense mechanism in the acute phase of hyperglycemia in which the number of insulin-IR myenteric neurons rapidly increased in response to the cessation of pancreatic insulin production." (PMID 40497986, 2025). "Despite persistent hyperglycemia (glucose = 165-245 mg/dL, hemoglobin A1c = 7.0-8.1%) and the need for frequent insulin dose adjustments due to poor glycemic control, the patient experienced recurrent episodes of overnight hypoglycemia despite insulin administration for carbohydrate intake." (PMID 41040769, 2025). "Progressive pancreatic impairment may further reinforce this systemic burden: reduced insulin secretion leads to hyperglycemia, which impairs multiple organ systems and exacerbates physical discomfort, while exocrine insufficiency results in maldigestion, further affecting abdominal discomfort." (PMID 41333788, 2025). "Indiscriminate perioperative cessation of a person’s non-insulin medicines with resultant loss of glycaemic control cannot be advocated, because this may lead to harm from either hyperglycaemia or harm from the use of exogenous insulin." (PMID 40651878, 2025). "Therefore, investigating the effects of acupuncture on blood glucose regulation may help establish its utility in treating hyperglycemia and improving insulin sensitivity in patients with PCOS." (PMID 40776915, 2025). "Drug treatment involves the implementation of insulin therapy, utilizing either human insulin, insulin analogs, or an expanding array of antihyperglycemic agents to achieve glycemic control, thus minimizing the effects of recurrent hypoglycemia and hyperglycemia." (PMID 40137145, 2025). "Indeed, short-term hyperglycemia can decrease the translocation of insulin-stimulated GLUT-4 transporters to the surface membrane of muscle cells and inhibit glucose transport, indicating a primary abnormality of glucose transport underlying muscle insulin resistance during hyperglycemia." (PMID 39998445, 2025). "In these studies, maternal diabetes and experimentally induced hyperglycaemia were found to result in asymmetrical growth patterns, increased insulin secretion and hyperplasia of insulin-producing beta cells during fetal development, followed by impaired insulin secretion in later life." (PMID 40603555, 2025).
Hyperglycemia (continued). "The mechanisms driving the proliferation of early β-cells could be reactivated in adult cells to increase the functional β-cell mass, especially during periods of high metabolic demand, such as pregnancy, weight gain, decreased insulin sensitivity or experimentally STZ-induced hyperglycemia." (PMID 39741186, 2025). "Lastly, hyperglycemia enlarges the infarct core in stroke patients, and in animal stroke models, hyperglycemia hastened the onset of cellular acidosis symptoms in the ischemic penumbra, resulting in a greater infarct size compared to hypoglycemic animals treated with insulin." (PMID 40281588, 2025). "Additionally, studies revealed that curcumin could prevent hyperglycemia by promoting insulin secretion, improving β-cell function, and inhibiting β-cell apoptosis." (PMID 40538540, 2025). "Consequently, altered muscle or adipose insulin sensitivity is unlikely to underlie αActRIIA/IIB-induced hyperglycemia." (PMID 41022302, 2025). "Hepatic steatosis, and excess fat in muscles and pancreas, may induce hyperglycemia by overproduction of glucose by the liver, reduction in insulin secretion by the pancreas, and decreased insulin-mediated glucose disposal due to muscle insulin resistance." (PMID 41009753, 2025). "Consequently, reliance solely on exogenous insulin can only mitigate symptoms; however, persistent hyperglycemia and inflammatory responses will further compromise pancreatic β-cells and potentially affect the entire pancreas, resulting in irreversible complications." (PMID 41185072, 2025). "Most individuals diagnosed with T2D exhibit adiposopathy-related diabetes (ARD), a condition characterized by hyperglycemia accompanied by three core features: increased ectopic and visceral fat deposition, dysregulated adipokine secretion favoring a pro-inflammatory state, and insulin resistance." (PMID 39941348, 2025). "Third, because stress hyperglycemia is dynamic, monitoring coupled with judicious insulin therapy may be particularly impactful in the COVID-AP interface, where glucocorticoids and vasopressors are frequently co-administered and iatrogenic glycemic excursions are common." (PMID 41010381, 2025). "Notably, patients in cluster 1 exhibited the lowest prevalence but the most unfavorable risk profile already early in pregnancy and were characterized by elevated lipids in addition to hyperglycemia, as well as beta-cell dysfunction and particularly impaired insulin sensitivity." (PMID 41156506, 2025). "Notably, patient P10 exhibited the highest level of hyperglycemia, which required insulin infusion." (PMID 40004108, 2025). "A study demonstrated that Wistar rats with streptozotocin (STZ)‐induced hyperglycemia, treated with methanolic and acetone extracts of P. florida (200 and 400 mg/kg for 4 weeks), exhibited reduced blood glucose levels and an improved lipid profile, accompanied by increased serum insulin levels." (PMID 40899490, 2025). "Additionally, sustained elevation of circulating FFAs (resulting from increased VAT lipolysis) induces pancreatic β-cell lipotoxicity via endoplasmic reticulum stress-mediated apoptosis and impaired glucose-stimulated insulin secretion, further exacerbating hyperglycemia and renal damage." (PMID 41393943, 2025). "Furthermore, diabetic patients may receive glucose management interventions, such as insulin therapy, which could mitigate the adverse effects of hyperglycemia on their prognosis to some extent." (PMID 40343929, 2025). "Interestingly, studies have also shown that oxidative stress disrupts signaling pathways related to glucose regulation, as well as the sensitivity of peripheral tissues to insulin, leading to IR, islet β cell dysfunction, and even islet cell damage and hyperglycemia." (PMID 40241987, 2025).
Hyperglycemia (continued). "In contrast, those with T2D have normal even much higher circulating insulin concentration as compared to healthy individuals, but their bodies are unable to effectively utilize the available insulin, leading to the coexistence of hyperglycemia and hyperinsulinemia simultaneously." (PMID 40013312, 2025). "The birth parameters of SGA itself support sustained and persistent intrauterine insulin deficiency, where insulin acts as a major fetal growth factor, such that postnatal insulin deficiency in the absence of overt hyperglycemia in the first 24 hours seems likely." (PMID 40979819, 2025). "Additionally, a recent investigation involving obese women with postprandial hyperglycemia employed microdialysis to show that higher circulating insulin levels were necessary to achieve interstitial insulin concentrations comparable to those in lean individuals." (PMID 40725728, 2025). "Due to the hyperglycemia in diabetic patients, GOx can extensively convert glucose into gluconic acid, which results in a decreased environmental pH, and thereby the GOx-based hydrogels with pH-responsive units can undergo swelling, shrinkage, or degradation to accelerate insulin release." (PMID 40292663, 2025). "For instance, prolonged hyperglycemia or lipid overload induces epigenetic alterations in macrophages, such as DNA methylation and histone modifications, which perpetuate pro-inflammatory phenotypes (e.g., sustained NF-κB activation) and impair insulin signaling pathways." (PMID 40453651, 2025). "Additionally, humoral factors, including pro-inflammatory cytokines, such as tumor necrosis factor-alpha (TNF-α), interleukin-6 (IL-6), and interleukin-1 beta (IL-1β), further exacerbate hyperglycemia by impairing insulin signaling and increasing hepatic glucose output." (PMID 40868089, 2025). "In addition, excessive gestational weight gain may expose the fetus to hyperglycemia, elevated insulin levels, and inflammatory cytokines, programming metabolic risk from early life." (PMID 41026769, 2025). "PTDM, defined as new-onset and persistent hyperglycaemia 3 months posttransplant in transplant recipients and present for more than 6 months, has characteristics and pathophysiological mechanisms similar to those of type 2 diabetes, e.g., insulin resistance or a decline in the production of insulin." (PMID 41013432, 2025). "Furthermore, the persistent psychological and logistical burdens associated with the use of automated insulin delivery systems and devices, alongside continuous risks of hypoglycemia and hyperglycemia, highlight the inherent limitations of current insulin-based strategies." (PMID 40904460, 2025). "Preclinical studies have demonstrated that PENPs can improve hyperglycemia, enhance insulin sensitivity, regulate hepatic lipid metabolism, and promote wound healing by modulating oxidative stress, inflammation, gut microbiota, glucose metabolism, and insulin signaling." (PMID 41009713, 2025). "Additionally, the diet’s capacity to improve insulin sensitivity, reduce weight, and attenuate antipsychotic-induced hyperglycemia offers a rare dual benefit: targeting both psychiatric symptoms and physical health comorbidities that contribute to early mortality." (PMID 40635756, 2025). "Assessments of ROS in conjunction with hyperinsulinemic–euglycemic clamp studies in younger Townes mice exhibiting hyperglycemia but comparable fasting insulin levels are essential to dissect differences in insulin sensitivity in Townes mice and the role ROS may have in the process." (PMID 40294908, 2025). "Additionally, intestinal permeability may make it easier for bacterial fragments to enter the body, engaged with the Toll‐like receptor to activate immunity, and result in resistance of insulin activity and hyperglycemia." (PMID 39803213, 2025). "Likewise, diminishing alpha-cell glucagon secretion via D2R agonism may concurrently lower hyperglycemia and improve both insulin resistance and overall glycemic control." (PMID 39906261, 2025).
Hyperglycemia (continued). "However, in T1DM, the absence of endogenous insulin secretion complicates glucose regulation, increasing the risk of both hypoglycemia and hyperglycemia." (PMID 40217942, 2025). "Moreover, reduced insulin levels may lead to increased glucagon secretion, further aggravating hyperglycemia through enhanced hepatic glucose output." (PMID 41465559, 2025). "NA is given 15 min before STZ to 2-month-old Wistar rats and causes mild and non-fasting hyperglycemia without a substantial depletion in plasma insulin concentration and a decrease in pancreatic insulin storage, making it a model of impaired insulin sensitivity." (PMID 40430475, 2025). "Despite persistent hyperglycemia, reflected in average blood glucose levels consistently above 245 mg/dL and elevated hemoglobin A1c values, the patient experienced recurrent episodes of overnight hypoglycemia, even when insulin was appropriately dosed for carbohydrate intake." (PMID 41040769, 2025). "This suggests that CS/Res/SeNPs could offer a novel strategy for improving T2DM management by normalizing serum biochemical parameters, treating hyperglycemia, improving insulin sensitivity, and attenuating oxidative stress, inflammation, and apoptosis in liver tissues." (PMID 40664894, 2025). "In this study, hyperglycemia was found to be a central driver of survival risk in patients with MASLD, which exacerbates the process of hepatic lipid deposition and fibrosis through multiple mechanisms, including insulin resistance, oxidative stress, and dysregulation of the gut-liver axis." (PMID 40533869, 2025). "Indeed, we observed impaired beta cell mass and insulin labeling with an increased proportion of glucagon-positive cells per islet, which could further contribute to overall hyperglycemia." (PMID 41017587, 2025). "Consequently, while insulin therapy remains a recommended strategy for managing hyperglycemia in hospitalized patients, concerns about hypoglycemia have prompted leading professional organizations worldwide to revise their glucose target recommendations and antidiabetic medication selections." (PMID 40901501, 2025). "By combining automated delivery of glucagon alongside insulin, these systems aim to not only correct hyperglycaemia but also prevent or rapidly correct hypoglycaemia, something that insulin-only systems inherently struggle with due to the delayed pharmacokinetic profile of insulin analogues." (PMID 40718205, 2025). "This is explained by the fact that hyperglycemia in the mother can result in excessive glucose consumption by newborns, which may lead to hyperplasia of fetal pancreatic beta cells and an increase in insulin and insulin-like growth factor levels." (PMID 40953062, 2025). "Lipolysis is highly sensitive to insulin so that differences between studies could at least partly result from overnight insulin administration to reduce hyperglycemia before beginning the clamps or from the high clamp insulinemia, which leads to complete suppression of lipolysis in T1D." (PMID 39998445, 2025). "Similarly, in cases of stress-induced hyperglycemia, applications might suggest guided relaxation techniques or adaptive insulin dosing strategies tailored to real-time physiological responses." (PMID 40742490, 2025). "Therefore, SMTNL1 may be a feasible therapeutic target for progesterone-dependent inhibition of endometrial epithelial cells during hyperglycemia and insulin-sensitizing endometrium in gestational diabetes or other metabolic disorders." (PMID 38883605, 2024). "We hypothesized that hyperglycemia potentiates insulin secretion in response to ucOC stimulation." (PMID 39125265, 2024). "However, insulin therapy could preserve testicular redox balance against T1D-induced hyperglycemia, indicating that hyperglycemia directly impacts the redox homeostasis in testicular tissue." (PMID 38164482, 2024).